SDC3 (syndecan 3)
Description:
Cell surface proteoglycan that may bear heparan sulfate (By similarity). May have a role in the organization of cell shape by affecting the actin cytoskeleton, possibly by transferring signals from the cell surface in a sugar-dependent mechanism.
Synonyms: SYND3; N-syndecan; SDCN
Tractability: Antibody: its Gene Ontology location is reachable by antibodies, with high confidence; UniProt places it where antibodies can reach, with medium confidence; UniProt predicts a signal peptide or a membrane-spanning region. PROTAC: ubiquitination databases record sites on it; its protein half-life has been measured.
Gene: Protein-coding gene on chromosome 1 (30,869,466 to 30,908,810, reverse strand). Ensembl gene ENSG00000162512.
Subcellular location: Cell membrane
Subcellular location (Human Protein Atlas): Mitochondria; Nucleoplasm
Pathways (Reactome):
Disease: Attachment and Entry; Defective B3GALT6 causes EDSP2 and SEMDJL1; Defective B3GAT3 causes JDSSDHD; Defective B4GALT7 causes EDS, progeroid type; Defective EXT1 causes exostoses 1, TRPS2 and CHDS; Defective EXT2 causes exostoses 2; Dengue Virus Attachment and Entry; Dengue Virus-Host Interactions; RSV-host interactions; Respiratory syncytial virus (RSV) attachment and entry
Hemostasis: Cell surface interactions at the vascular wall; Initiation of coagulation cascade; Regulation of clotting cascade
Metabolism: Glycosaminoglycan-protein linkage region biosynthesis; HS-GAG biosynthesis; HS-GAG degradation
Extracellular matrix organization: Syndecan interactions
Sensory Perception: Retinoid metabolism and transport
Gene Ontology:
Molecular function: identical protein binding; protein binding
Cellular component: extracellular matrix; cell surface; Golgi lumen; lysosomal lumen; membrane; microspike; plasma membrane
Genetic constraint (gnomAD): Loss-of-function variants: 9 observed, 21.53 expected, observed/expected ratio (o/e) 0.42, 90% interval 0.25 to 0.73. The upper end of that interval is the gene's LOEUF score, 0.73, which puts it in group 2 of 6, group 1 being the genes least tolerant of losing a copy. Missense variants: 518 observed, 551.03 expected, observed/expected ratio (o/e) 0.94, 90% interval 0.87 to 1.01. Synonymous variants: 266 observed, 236.54 expected, observed/expected ratio (o/e) 1.12, 90% interval 1.02 to 1.25.
Homologues: Orthologues: dog SDC3 (92% identical), chimpanzee SDC3 (91% identical), macaque SDC3 (90% identical), mouse Sdc3 (83% identical), rabbit SDC3 (83% identical), guinea pig SDC3 (81% identical), rat Sdc3 (77% identical), pig SDC3 (71% identical), tropical clawed frog sdc3 (40% identical), Drosophila melanogaster Sdc (23% identical), Caenorhabditis elegans sdn-1 (14% identical). Paralogues in human: SDC1 (24% identical), SDC4 (18% identical), SDC2 (16% identical).
Diseases named in the same sentence as SDC3 in open-access papers:
SDC3 is named in the same sentence as 74 diseases in open-access papers, as found by Europe PMC text mining. Sharing a sentence is not in itself a finding about the gene and the disease. The quoted sentences say what the papers report.
ovarian carcinoma (12 papers, 2007 to 2025). A malignant neoplasm originating from the surface ovarian epithelium. "SDC3 has previously been associated with the pathogenesis of ovarian cancer, pancreatic cancer, and renal cell carcinoma." (PMID 41148827, 2025). "While these data point to a potential role for SDC3 in ovarian cancer pathogenesis, its full diagnostic impact and its functional relevance are not clear." (PMID 35628603, 2022). "Our study suggests that up-regulation of syndecan-3 promotes the pathogenesis of ovarian cancer by modulating stemness-associated pathways." (PMID 35628603, 2022). "In summary, our study has demonstrated that SDC3 is over-expressed in ovarian cancer and that its upregulation is associated with a poor prognosis in the subgroup of patients receiving Taxol and cisplatin chemotherapy." (PMID 35628603, 2022). "One potential biomarker that could be mechanistically linked to the pathogenesis of ovarian cancer is syndecan-3 (SDC3)." (PMID 35628603, 2022). "Consistent with this concept, our KM Plotter analysis revealed that a high SDC3 expression was associated with worse survival in ovarian cancer patients treated with Taxol and platin chemotherapy, indicating a possible functional role for SDC3 in resistance to chemotherapy." (PMID 35628603, 2022). "SDC3 is associated with an EMT-stemness phenotype in ovarian cancer." (PMID 36358747, 2022). "Supporting this theory, a study on ovarian cancer found that SDC3 RNA expression was higher in primary tumors compared to metastatic sites, further indicating the potential association of the molecule with early-stage cancer progression." (PMID 41148827, 2025). "Our qPCR analysis revealed that several constituents of stemness-related signaling pathways were dysregulated upon SDC3 depletion in ovarian cancer cells in vitro, the most notable constituents of the Notch, Wnt and hedgehog pathways." (PMID 35628603, 2022). "In this study, we assess the expression of SDC3 in ovarian cancer tissue and metastases using large public datasets and perform functional investigations using an siRNA approach in the model cell line SKOV3." (PMID 35628603, 2022). "Previous studies on the expression of SDC3 in ovarian cancer had pointed to its misexpression in diseased tissue and possible utility as a biomarker, however, the reported data fell short of significance and revealed only trends." (PMID 35628603, 2022). "Through the in silico analysis of large public gene expression datasets, we were now able to demonstrate that SDC3 mRNA expression is highly significantly upregulated in ovarian cancer tissue in comparison with control tissue." (PMID 35628603, 2022). "In particular, silencing of SDC3 reduces colony formation and 3D spheroid growth and stemness in ovarian cancer cells." (PMID 36358747, 2022). "In a study published in 2019, SDC3 was identified as a biomarker in ovarian cancer using data mining approaches including datasets of micro-dissected epithelial and stromal cells of ovarian cancers." (PMID 35628603, 2022). "We analyzed public gene expression datasets to evaluate the dysregulation and potential prognostic impact of Syndecan-3 in ovarian cancer." (PMID 35628603, 2022). "In a study, SDC3 mRNA expression was evaluated in whole blood samples from healthy donors and patients with either benign or malignant ovarian tumors." (PMID 35628603, 2022). "Elevated expression levels of SDC3 have been reported in bladder and ovarian cancer, and renal cell carcinoma, whereas low levels of SDC3, SDC4, GPC1, and GPC3 are expressed in neuroblastoma." (PMID 32916872, 2020). "In previous studies, we showed that stromal syndecan 1 was an adverse prognostic factor in ovarian cancer and that syndecan 3, which is usually found on neuronal tissue, was aberrantly expressed in the tumour vasculature." (PMID 17437011, 2007).
ovarian carcinoma (continued). "In a previous study of HSPGs, we showed that stromal syndecan 1 was an adverse prognostic factor for ovarian cancer and that syndecan 3 was unusually expressed by the vasculature." (PMID 17437011, 2007). "Among these three miRNAs, only miR-138-5p has published evidence that it was directly targeted by lncRNA TRPM2-AS and thus regulating downstream signaling, e.g., PI3K/AKT in non-small cell lung cancer, syndecan 3 (SDC3) in ovarian cancer, and urokinase in gastric adenocarcinoma." (PMID 35156509, 2022). "A potential role in the pathogenesis of ovarian carcinoma was already attributed to SDC3 in 2004." (PMID 35628603, 2022). "Our in vitro findings are in line with this hypothesis, as SDC3 knockdown in ovarian cancer cells primarily affected cell viability (as a readout of tumor growth), but not cell motility as one of the prerequisites for metastatic spread." (PMID 35628603, 2022). "SDC3 has not been widely studied with respect to either breast or ovarian carcinoma, but its aberrant upregulation in vasculature associated with ovarian carcinoma has been noted." (PMID 25140302, 2014). "The upregulation of syndecan-3 (SDC3), has been demonstrated in various gene expression datasets, highlighting their utility in identifying the presence of ovarian cancer and even distinguishing metastatic lesions." (PMID 40836974, 2024). "While some cell-type-specific differences were observed (see discussion), we conclude that SDC3 depletion in SKOV3 and CAOV3 ovarian cancer cells resulted in a downregulation of stemness-related constituents of the Notch, Wnt, and hedgehog pathways." (PMID 35628603, 2022). "Moreover, we performed functional in vitro analysis in syndecan-3-siRNA-treated SKOV3 and CAOV3 ovarian cancer cells." (PMID 35628603, 2022). "However, VCAN and SDC3 transcripts were elevated in the blood of ovarian cancer patients and showed a considerable trend toward significance (P-values: VCAN = 0.052, SDC3 = 0.055)." (PMID 31336942, 2019). "Therefore, our data may point to a potential role for SDC3 in chemoresistance in a subgroup of ovarian cancer patients rather than a general link to therapeutic resistance in ovarian cancer." (PMID 35628603, 2022).
melanoma (8 papers, 2020 to 2025). A malignant, usually aggressive tumor composed of atypical, neoplastic melanocytes. "This difference was only present in highly hypoxic tumors, suggesting that Sdc-3 expression is associated with hypoxia and a proinflammatory immune response, leading to better patient OS in melanoma." (PMID 33117401, 2020). "Using single-cell RNA sequencing data of melanoma patients, we show that Sdc-3 is expressed on tumor associated macrophages, cancer cells, and endothelial cells." (PMID 33117401, 2020). "SDC3 was specifically increased in melanoma and two brain tumors, glioma and glioblastoma multiforme." (PMID 35850748, 2022). "SDC3 expression is boosted by hypoxia in the tumor microenvironment, which influences pro-inflammatory reactions and the overall survival of melanoma patients." (PMID 36189226, 2022). "SDC3 is specifically increased in melanoma and brain tumors, but SDC2 and GPC3 are up-regulated in HCC." (PMID 35850748, 2022). "Studies have shown that hypoxia can promote the expression of Syndecan-3 so that patients with melanoma tumors have a better overall survival rate." (PMID 36387908, 2022). "In addition to tumor cells, we identified TAMs as the main stromal compartment expressing Sdc-3 in the TME based on scRNA-seq data from melanoma patients." (PMID 33117401, 2020). "Syndecan-3 expression correlates with a better patient overall survival in hypoxic melanoma tumors." (PMID 33117401, 2020). "Also in melanoma, Sdc3 expression is induced by hypoxia-inducible factors such as HIF1α." (PMID 35628603, 2022). "SDC3 could also promote melanoma tumors through the regulation of the HIF pathway." (PMID 34987579, 2021). "Hypoxia has been shown that in studies to promote the expression of Syndecan-3 (SDC3) on macrophages, which is positively correlated with macrophage gene markers, resulting in a better overall survival rate for melanoma tumor patients." (PMID 38586328, 2024). "SDC3 and SDC4 genes expression levels were the highest on melanoma cells and were also present on macrophages and endothelial cells but absent on B and T cells." (PMID 33117401, 2020). "In order to examine the expression of Sdc-3 and Sdc-4 in the TME, we analyzed single-cell RNA sequencing (scRNA-seq) data from melanoma patients, which was the solid tumor type with the highest ratio of expression of Sdc-3 on malignant/normal tissue based on TCGA database." (PMID 33117401, 2020).
Obesity (8 papers, 2012 to 2025). Accumulation of substantial excess body fat. "Syndecan-3 (SDC3), a heparin sulfate proteoglycan, had been found by previous studies to be linked with energy balance and obesity." (PMID 36447229, 2022). "Two SNPs in SDC3 result in conservative amino acid changes in the core protein extracellular domain associate with obesity in a Korean population." (PMID 33561383, 2021). "One variant in the SDC3 gene (rs2282440), which is associated with obesity in Asians has a significantly increased frequency in Roma (19%) and it is virtually absent in other European groups." (PMID 34220960, 2021). "Strong association between the SDC3 SNP rs2282440 and obesity had been shown in a Korean study and also confirmed in the Taiwanese population." (PMID 29666642, 2018). "The results indicate that heparanase inhibits obesity by degrading HS chains, presumably linked to syndecan-3, thereby suppressing the binding of AgRP to MC4R." (PMID 22479599, 2012). "In humans, SDC3 polymorphisms have been linked to obesity and female hyperandrogenemia." (PMID 36613828, 2022). "Notably, a polymorphism in the syndecan-3 gene has been associated with obesity in a female population." (PMID 22479599, 2012). "In addition, SDC3 rs2282440 polymorphism was associated with obesity (p = 0.0058)." (PMID 29666642, 2018). "The linkage to lipid metabolism has also been recorded in mice, where the syndecan-3 null is resistant to diet-induced obesity." (PMID 33561383, 2021). "Syndecan-3 (SDC3), a heparin sulfate proteoglycan, had been found by previous studies to be linked with energy balance and obesity, but its association with MetS is not known." (PMID 29666642, 2018). "Indeed, mice that lack syndecan-3 have a reduced fat mass and are protected against diet-induced obesity." (PMID 22479599, 2012).
breast carcinoma (7 papers, 2013 to 2024). "However, no study has yet revealed this miRNA-dependent regulation for SDC3, which has been shown to be expressed in mammary carcinoma tissues and strongly linked to the overall survival of breast cancer patients." (PMID 36980680, 2023). "Studies have also shown that the expression of SDC-3 protein has an excellent predictive value for the prognosis of breast cancer." (PMID 36387908, 2022). "Until recently, SDC3, as one of the hypoxia-related gene, along with other 13 genes was found to be a potential prognostic biomarker for breast cancer." (PMID 34109210, 2021). "Knock down of syndecan-3 in endothelial,- smooth muscle- and breast cancer cells reduced the TFPI surface levels by 20-50%, and an association of TFPIα to syndecan-3 on the cell surface was demonstrated." (PMID 25617766, 2015). "We determined the mRNA and protein expression of three proteins demonstrated to bind ARTN, namely GFRα1, GFRα3 and Syndecan-3 (SDC3), in benign breast disease and mammary carcinoma by in situ hybridization and immunohistochemistry, respectively." (PMID 23351331, 2013). "The expression of GFRα1 and GFRα3, but not SDC3, was significantly increased in mammary carcinoma and positively associated with tumor lymph node metastases, higher clinical stage and HER-2 positivity." (PMID 23351331, 2013). "Moreover, both GFRα1 and GFRα3 expression were significantly associated with survival outcome of patients with mammary carcinoma by univariate and multivariate analyses, whereas expression of SDC3 was not." (PMID 23351331, 2013). "Previous research has indicated that PGK1, SDC1, SDC3, NUP43, and IL13RA1 may contribute to the development and progression of breast cancer." (PMID 39590319, 2024). "Co-expression of ARTN with either GFRα1 or GFRα3, but not SDC3, produced synergistic increases in the odds ratio for both relapse-free and overall survival in patients with mammary carcinoma." (PMID 23351331, 2013).
glioma (6 papers, 2018 to 2025). A benign or malignant brain and spinal cord tumor that arises from glial cells (astrocytes, oligodendrocytes, ependymal cells). "The TRPV2 interactome showed a high association with early glia-related neoplasms, especially glioma/glioblastoma, being ABR, FGF1, KCNJ10, PEBP1, PLP1, SDC3, and TRPV2, the genes associated to these brain neoplasms." (PMID 29719613, 2018). "MES-like glioma cells expressed multiple receptors for ANGPTL4, including syndecans SDC2, SDC3, and SDC4 as well as WNT5A receptor FZD6, suggesting that these pathways may be responsible for the enrichment of GSCs in ECMhi tumors." (PMID 37292803, 2023).
Arthritis (5 papers, 2014 to 2025). Inflammation of a joint. "However, the effects of loss of sdc-3 in the arthritis model may be mediated, at least in part, by cells other than endothelial cells, since sdc-3 is also expressed by chondrocytes." (PMID 25015005, 2014). "The selective expression of endothelial SDC3 was already explored in the chronically inflamed synovium, where SDC3 plays a part in arthritis pathophysiology by binding cytokines and modulating the migration and retention of leukocytes." (PMID 35328830, 2022). "In the current work experiments, MSC treatments (wild type and Sdc3−/−) significantly reduced exudates in the joint cavity and cartilage loss at day 3 following MSC treatment and the overall arthritis index at day 3 post-arthritis induction." (PMID 33235244, 2020). "The authors show that soluble SDC3 binds chemokines, reduces leukocyte migration in vitro and ameliorates disease severity in mouse models of arthritis." (PMID 33235244, 2020). "MSC treatments (wild type and Sdc3−/−) reduced joint swelling as a measure of joint inflammation compared to serum-free medium control at days 2 (p < 0.05) and 3 (p < 0.05) post arthritis induction." (PMID 33235244, 2020). "Soluble syndecan-3 was tested in antigen-induced and collagen-induced in vivo arthritis models in mice." (PMID 31300004, 2019). "Further studies involving conditional deletion of sdc-3 in selected cell types and examining the effect on arthritis severity would be of interest in this respect." (PMID 25015005, 2014). "Chemokine C-X-C ligand 1 (CXCL1) was injected in the joints of syndecan-3−/−and wild-type mice and antigen-induced arthritis performed." (PMID 25015005, 2014). "This suggests that sdcs may be involved in various aspects of joint inflammation and damage in arthritis, with endothelial sdc-3 functioning in leukocyte recruitment and fibroblast sdc-4 in cartilage destruction." (PMID 25015005, 2014). "Furthermore, in the arthritis model syndecan-3 deletion led to reduced joint swelling, leukocyte accumulation, cartilage degradation and overall disease severity." (PMID 25015005, 2014).
rheumatoid arthritis (5 papers, 2014 to 2022). A chronic, systemic autoimmune disorder characterized by inflammation in the synovial membranes and articular surfaces. "Increased expression of SDC3 has been shown on endothelia in rheumatoid arthritis and psoriasis arthritis synovium comparing to normal synovium, which is thought to have roles in angiogenesis, chemokine presentation and leukocytes extravasation." (PMID 36059983, 2022). "Syndecan-3, the least well-characterised of the syndecan family, is highly expressed on synovial endothelial cells in rheumatoid arthritis patients." (PMID 31300004, 2019). "The purpose of the remainder of this review is to examine the roles of SDC3 in the context of inflammatory disease (rheumatoid arthritis), angiogenesis and also HIV infection." (PMID 31998313, 2019). "Furthermore, soluble syndecan-3 occurred naturally in the sera of patients with rheumatoid arthritis and periodontitis, and its levels correlated with syndecan-1." (PMID 31300004, 2019). "Recent studies suggest that SDC3 expression is not restricted to neuronal tissues and has important roles in inflammatory disorders such as rheumatoid arthritis, disease associated processes such as angiogenesis and in the facilitation of infection of dendritic cells by HIV." (PMID 31998313, 2019). "Syndecan-3 is expressed by synovial endothelial cells of rheumatoid arthritis (RA) patients where it binds chemokines, suggesting a role in leukocyte trafficking." (PMID 25015005, 2014). "Using in vitro and in vivo models, soluble syndecan-3 inhibited leukocyte migration in vitro in response to CCL7 and its administration in murine models of rheumatoid arthritis reduced histological disease severity." (PMID 31300004, 2019).